C10orf71 (chromosome 10 open reading frame 71)
Description:
Is an activator of the calcineurin/NFAT signaling pathway in cardiomyocytes, and is involved in myocardium morphogenesis, and regulation of myocardium mass and cardiac contractile function.
Synonyms: CEFIP; FLJ45913; CMD1QQ
Tractability: No criterion of Open Targets' tractability assessment is met for any kind of drug.
Gene: Protein-coding gene on chromosome 10 (49,299,165 to 49,327,492, forward strand). Ensembl gene ENSG00000177354.
Subcellular location: Cytoplasm, myofibril, sarcomere, Z line
Subcellular location (Human Protein Atlas): Nucleoplasm; Mitochondria
Gene Ontology:
Molecular function: protein binding
Biological process: positive regulation of calcineurin-NFAT signaling cascade
Cellular component: Z disc
Genetic constraint (gnomAD): Loss-of-function variants: 0 observed, 0.94 expected, observed/expected ratio (o/e) 0, 90% interval 0 to 1.74. That is too few expected variants to judge how well the gene tolerates losing a copy. Missense variants: 1,869 observed, 1,878.5 expected, observed/expected ratio (o/e) 0.99, 90% interval 0.96 to 1.03. Synonymous variants: 758 observed, 757.4 expected, observed/expected ratio (o/e) 1, 90% interval 0.94 to 1.06.
Homologues: Orthologues: macaque C9H10orf71 (94% identical), chimpanzee C10H10orf71 (88% identical), pig C10orf71 (73% identical), dog C10orf71 (73% identical), rat C16h10orf71 (66% identical), mouse 3425401B19Rik (65% identical), guinea pig C10orf71 (63% identical), rabbit C10orf71 (61% identical), tropical clawed frog c7h10orf71 (24% identical).
Diseases named in the same sentence as C10orf71 in open-access papers:
C10orf71 is named in the same sentence as 9 diseases in open-access papers, as found by Europe PMC text mining. Sharing a sentence is not in itself a finding about the gene and the disease. The quoted sentences say what the papers report.
dilated cardiomyopathy (2 papers, 2024). Cardiomyopathy which is characterized by dilation and contractile dysfunction of the left and right ventricles. "The dilated cardiomyopathy gene C10orf71 affects cardiac morphology and contractile function." (PMID 38950288, 2024).
cardiomyopathy (1 paper, 2024). A disease of the heart muscle or myocardium proper. "Third, this study focused on DCM, and screening for C10orf71 variants in other cardiomyopathy cohorts could inform other types of cardiomyopathies including LVNC." (PMID 38950288, 2024). "In vivo experiments of the role of C10orf71 in the pathogenesis of cardiomyopathy have not been reported." (PMID 38950288, 2024).
virus infection (1 paper, 2018). "The expression of the most suppressed RNA, C10orf71, was suppressed only 50-fold by virus infection while the most induced RNA, IL29, was induced almost 20,000-fold." (PMID 30429577, 2018).
cardiovascular disease (2 papers, 2024). "As the C10orf71 gene had not previously been associated with cardiovascular disease, we examined tissue-specific expression of the gene and found that it was almost exclusively expressed in muscle tissue (eFigure 5 in Supplement 1)." (PMID 38922602, 2024).
cancer (1 paper, 2020). A tumor composed of atypical neoplastic, often pleomorphic cells that invade other tissues. "However, the SPIN4 and C10orf71 have not been reported associated with the development and progression of cancer." (PMID 31701684, 2020).
C10orf71 also shares sentences with these, for which no sentence is quoted: Bradycardia (1 paper); cardiac hypertrophy (1); kidney cancer (1); Wilms tumor (1).